AMD1 (adenosylmethionine decarboxylase 1)
Diseases named in the same sentence as AMD1 in open-access papers (continued):
Sharing a sentence is not in itself a finding about the gene and the disease.
cancer (14 papers, 2016 to 2025). A tumor composed of atypical neoplastic, often pleomorphic cells that invade other tissues. "We also found that triptolide downregulated AMD1, which is upregulated in many cancers and is associated with patient prognosis." (PMID 35366242, 2022). "For example, elevated levels of polyamines and the polyamine biosynthetic enzymes ODC and AMD1 are often associated with hyper-proliferative phenotypes and are overexpressed in many cancer types." (PMID 34068137, 2021). "Furthermore, FTO-mediated RNA demethylation was also involved in S-adenosylmethionine decarboxylase proenzyme (AMD1)-induced cancer stemness in HCC." (PMID 35859892, 2022). "mTOR was also recently shown to activate S-adenosylmethionine decarboxylase proenzyme (AMD1), which phosphorylates obesity-associated protein (FTO) and subsequently increases the expression of a number of transcription factors that participate in cancer genesis, progression, and stemness." (PMID 35785216, 2022). "Finally, the methionine salvage pathway can also affect AMD1 and polyamine levels in cancer." (PMID 34068137, 2021). "It means AMD1 and other enzymes participating in the polyamines metabolism may become potential candidate for differential diagnoses HCC with other cancers." (PMID 33783988, 2021).
infection (6 papers, 2019 to 2025). The state of being infected such as from the introduction of a foreign agent such as serum, vaccine, antigenic substance or organism. "In general, despite temporal fluctuations in gene expression following infection, amd1 levels were higher in the liver of vaccinated and CTRL-fed fish compared to their respective naïve and MET-fed counterparts." (PMID 41256851, 2025). "Post-infection, amd1 levels gradually increased until 24 hpi and then subtly declined by 48 hpi." (PMID 41256851, 2025). "Meanwhile, the infection increased the mRNA transcription of MAT2A, AMD1, SMS, and AHCY mRNA with the same MOI." (PMID 38130504, 2024). "Another enzyme, S-adenosylmethionine decarboxylase (AMD1), which is a key enzyme for the synthesis of polyamines, showed a value of log2FC 1.49 at 3 DPI vs CK, indicating that fungal polyamine biosynthesis was up-regulated in the intermediate infection stage compared with the CK." (PMID 37330505, 2023).
AMD1 also shares sentences with these, for which no sentence is quoted: acute myeloid leukemia (1 paper); African sleeping sickness (1); allergic rhinitis (1); B cell lymphoma (1); deafness (1); dilated cardiomyopathy (1); glioblastoma (1); glioma (1); heart failure (1); Intellectual disability (1); leiomyosarcoma (1); malaria (1); neurodevelopmental disorder (1); ovarian carcinoma (1); papillary renal cell carcinoma (1); prostate tumor (1); schizophrenia (1); viral myocarditis (1).